GSTA4 (glutathione S-transferase alpha 4)
Description:
Conjugation of reduced glutathione to a wide number of exogenous and endogenous hydrophobic electrophiles. This isozyme has a high catalytic efficiency with 4-hydroxyalkenals such as 4-hydroxynonenal (4-HNE).
Synonyms: GSTA4-4; GTA4
Tractability: Small molecule: a structure with a bound ligand is known; it has a high-quality binding pocket. PROTAC: ubiquitination databases record sites on it; its protein half-life has been measured.
Target class: Enzyme; Transferase
Gene: Protein-coding gene on chromosome 6 (52,977,948 to 52,995,312, reverse strand). Ensembl gene ENSG00000170899.
Subcellular location: Cytoplasm
Pathways (Reactome):
Metabolism: Glutathione conjugation
Gene Ontology:
Molecular function: glutathione transferase activity; identical protein binding; protein binding; protein homodimerization activity
Biological process: glutathione metabolic process; xenobiotic metabolic process
Cellular component: cytosol; cytoplasm
Genetic constraint (gnomAD): Loss-of-function variants: 5 observed, 11.97 expected, observed/expected ratio (o/e) 0.42, 90% interval 0.22 to 0.88. The upper end of that interval is the gene's LOEUF score, 0.88, which puts it in group 3 of 6, group 1 being the genes least tolerant of losing a copy. Missense variants: 114 observed, 133.06 expected, observed/expected ratio (o/e) 0.86, 90% interval 0.74 to 1. Synonymous variants: 44 observed, 46.96 expected, observed/expected ratio (o/e) 0.94, 90% interval 0.74 to 1.21.
Homologues: Orthologues: chimpanzee GSTA4 (99% identical), macaque GSTA4 (98% identical), pig GSTA4 (93% identical), dog GSTA4 (93% identical), guinea pig GSTA4 (92% identical), rabbit GSTA4 (89% identical), zebrafish gstp1.1 (29% identical), tropical clawed frog gstp1 (26% identical), Caenorhabditis elegans gst-29 (26% identical), Caenorhabditis elegans gst-3 (26% identical), Caenorhabditis elegans gst-9 (26% identical), Caenorhabditis elegans gst-11 (25% identical), and 35 more. Paralogues in human: GSTA2 (54% identical), GSTA1 (53% identical), GSTA3 (53% identical), GSTA5 (53% identical), GSTP1 (28% identical), GSTM1 (23% identical), GSTM2 (23% identical), GSTM4 (23% identical), GSTM3 (22% identical), GSTM5 (21% identical), HPGDS (20% identical).
Diseases named in the same sentence as GSTA4 in open-access papers:
GSTA4 is named in the same sentence as 70 diseases in open-access papers, as found by Europe PMC text mining. Sharing a sentence is not in itself a finding about the gene and the disease. The quoted sentences say what the papers report.
Obesity (11 papers, 2012 to 2025). Accumulation of substantial excess body fat. "We then determined if the beneficial effect of Chchd10 deficiency in combating obesity and insulin resistance (IR) is mediated through upregulating GSTA4." (PMID 39985288, 2025). "It has been found that altered oxidative stress and inflammatory responses in adipose tissue caused by obesity are closely related to the down-regulation of Gsta4." (PMID 38068762, 2023). "Genes belonging to the GST superfamily have been studied in metabolic disorders; for example, GSTA4 has been shown to be downregulated in obese individuals in relation to the inflammatory state associated with obesity, and GSTM1 null-polymorphisms have been linked to coronary heart disease." (PMID 39519120, 2024). "Also, 4 of these DEGs have a known-role in placenta development and function (ALCAM, BRCA1 GP2, GSTA4) and 5 are associated with obesity and insulin resistance (MPHOSPH9, BRCA1, ASP, ALCAM, GP2)." (PMID 30305020, 2018). "On the other hand, Chchd10 reduction‐mediated upregulation of GSTA4 improves mitochondrial functions to prevent adipocyte hypertrophy and combat obesity." (PMID 39985288, 2025). "Through activating the TDP43/Raptor/p62/Keap1/NRF2 axis, the reduction of Chchd10 in response to energy surplus awakens the adaptive response, which potentiates adipogenesis and GSTA4‐mediated 4‐HNE clearance to combat obesity." (PMID 39985288, 2025). "Consistent with the present finding, disruption of Gsta4 in mice increased 4-HNE levels and caused obesity in mice." (PMID 37749090, 2023). "In the same way, it has been described that GSTA4 expression is downregulated in the adipose tissue from obese insulin-resistant C57BL/6 J mice and in humans with obesity-linked IR." (PMID 31049126, 2019). "GSTA4 expression is diminished in obese insulin-resistant C57BL/6J mice and in humans with obesity-linked IR32." (PMID 31273281, 2019). "In recent years, obesity has been found to be correlated with a lower level of glutathione S-transferase A4 (GSTA4), which is an important enzyme responsible for the depredation of acetaldehyde (an established carcinogen metabolized from alcohol)." (PMID 22296784, 2012). "Additionally, consistent with the elevated oxidative stress, the amount of GSTA4, an important enzyme that is responsible for the proper breakdown of acetaldehyde, has been found to decrease approximately 3-4-fold in obesity, resulting in an increased local toxicity of acetaldehyde." (PMID 22296784, 2012). "In this sense, the GSTA4 expression is down regulated in the adipose tissue from obese insulin- resistant C57BL/6 mice and in humans with obesity and IR." (PMID 33916540, 2021).
atherosclerosis (5 papers, 2012 to 2024). A disease characterized by the build-up of fatty material and calcium deposition in the arterial wall resulting in partial or complete occlusion of the arterial lumen. "GSTA4 is involved in detoxification of lipid peroxidation products and has been linked to atherosclerosis." (PMID 22719926, 2012). "GSTA4 is correlated with oxidative metabolism in several diseases including atherosclerosis, Alzheimer’s disease, and cancers." (PMID 35712475, 2022). "The results of RNA sequencing analysis showed that many antioxidant genes were enriched in Fluid shear stress and atherosclerosis pathway, including MGST1, GSTM3, GSTA1, SOD2 and GSTA4." (PMID 36978937, 2023). "In addition, GSTA4, RAPGEF3, TRPV4, INSIG1, UTS2, and PPP1R1A all play a role in the development of atherosclerosis." (PMID 39758846, 2024).
Insulin resistance (5 papers, 2018 to 2025). Increased resistance towards insulin, that is, diminished effectiveness of insulin in reducing blood glucose levels. "It has been demonstrated that downregulation of GSTA4 in adipose tissue led to increased ROS production, protein carbonylation, and mitochondrial dysfunction contributing to the development of insulin resistance." (PMID 33643424, 2021). "In addition, Rha treatment modulated insulin resistance and increased gene expression of antioxidant enzymes (Cat, Sod2, Gpx3, Mgst1, Prdx3, Gsta4, Gsr, and Sod1) in the ovaries of the PCOS rats." (PMID 35663203, 2022).
skin cancer (5 papers, 2014 to 2025). "From these earlier studies, glutathione S-transferase alpha 4 (Gsta4) was identified as a skin tumor promotion susceptibility gene that maps within the Psl1.2 locus." (PMID 24700353, 2014). "Previous studies have shown that one gene that resides in this region (Gsta4) is a modifier of skin tumor promotion susceptibility." (PMID 24700353, 2014). "These analyses indicate that Psl1 is a compound locus with at least six genes, including Gsta4, that modify skin tumor promotion susceptibility." (PMID 24700353, 2014). "Inheritance of Psl1.1a, Psl1.2a, Psl1.2b, and Gsta4 from DBA/2 results in increased susceptibility to skin tumor promotion whereas inheritance of Psl1.1b and Psl1.2c from DBA/2 results in decreased susceptibility." (PMID 24700353, 2014). "GSTA4 is associated with certain types of human cancers, for example, GSTA4 mutation significantly increases susceptibility to human skin cancer and chemical-induced murine skin cancer, suggesting a protective role of GSTA4 against skin cancer." (PMID 37810110, 2023). "Furthermore, Psl1 was shown to consist of at least two subloci (i.e., Psl1.1 and Psl1.2) and that glutathione S-transferase alpha 4 (Gsta4), which maps to Psl1.2, is a skin tumor promotion susceptibility gene." (PMID 24700353, 2014). "The skin tumor promotion susceptibility locus, Psl1, was previously mapped to a 59.1-Mb region of mouse chr 9 and the glutathione S-transferase gene, Gsta4, was shown to underlie at least some of the effect of this locus on skin tumor promotion susceptibility in mice." (PMID 24700353, 2014). "Single-nucleotide polymorphisms of the GSTA4 gene are associated with an increased risk of human nonmelanoma skin cancer, and inactivation of Gsta4 increases susceptibility to skin cancer in a murine model." (PMID 35936694, 2022). "Additionally, inheritance of the DBA/2 allele of four of these loci (Psl1.1a, Psl1.2a, Psl1.2b, Gsta4) results in increased sensitivity whereas inheritance of the DBA/2 allele of two loci (Psl1.1b, Psl1.2c) results in decreased sensitivity to skin tumor promotion." (PMID 24700353, 2014). "Given the roles of GSTA4 in detoxifying 4-HNE and preventing skin cancer, we investigated the impact of Gsta4 inactivation in E. faecalis-induced colitis and CRC." (PMID 39819335, 2025).
colorectal cancer (4 papers, 2022 to 2025). A primary or metastatic malignant neoplasm that affects the colon or rectum. "Macrophage-specific expression of GPX4 decreased in both human COAD and READ compared to the corresponding normal tissues (p < 0.001 and 0.01 for COAD and READ, respectively), suggesting that decreased expression of GSTA4 may be associated with macrophage ferroptosis in human colorectal cancer." (PMID 39819335, 2025). "In line with animal studies, our analysis of human data from TCGA and IBD databases suggests a potential link between reduced GSTA4 expression and macrophage ferroptosis, especially in cases of human colorectal cancer." (PMID 39819335, 2025). "Exposure to 4-HNE has also been reported to increase the expression of AKR1C in the human neuroblastoma cell line SH-SY5Y and that of glutathione S-transferase alpha 4 (GSTA4), one of the isoforms of GSTs, in colorectal cancer." (PMID 37626774, 2023). "GSTA4 is overexpressed in several types of human cancer including breast, kidney, liver, and colorectal cancer." (PMID 37810110, 2023). "Glutathione S-transferase alpha 4 (GSTA4) is a phase II detoxifying enzyme that is overexpressed in colorectal cancer (CRC) and regulated by the oncogenic transcription factor AP-1." (PMID 35936694, 2022). "GSTA4 is overexpressed in the colon biopsies of human colorectal cancer and the bacteria-induced murine CRC model through activating oncogenic transcription factor activator protein 1 (AP-1)." (PMID 35936694, 2022). "However, few studies have assessed the value of GSTA4 as a biomarker for colorectal cancer so far." (PMID 37810110, 2023). "However, little is known whether this highly expressed GSTA4 contributes to the progression and/or chemoresistance of colorectal cancer (CRC)." (PMID 35936694, 2022). "To investigate whether GSTA4 is involved in chemoresistance, we determined cell survival rates for HCT116 and HCT116ΔGSTA4 cells after exposure to 5-FU and oxaliplatin, two first-line chemotherapeutic agents for colorectal cancer." (PMID 35936694, 2022).
glioblastoma (4 papers, 2022 to 2026). The most malignant astrocytic tumor (WHO grade IV). "Further comparison of the expression levels of GSTA4 in low‐grade gliomas and glioblastomas showed that the expression level of GSTA4 in glioblastomas was significantly higher than that in low‐grade gliomas." (PMID 35048517, 2022). "The results here show that GSTA4 is highly expressed in both low‐grade gliomas and glioblastomas, but that the expression level of GSTA4 in glioblastomas is much higher than that in low‐grade gliomas." (PMID 35048517, 2022). "In order to confirm whether the expression of GSTA4 is upregulated in malignant gliomas, we detected the expression of GSTA4 in four cases of low‐grade gliomas and eight cases of glioblastomas by Western blot." (PMID 35048517, 2022). "Moreover, there is benzofuran, 6-ethenyl-4,5,6,7-tetrahydro-3,6-dimethyl-5-isopropenyl-, trans- or curzerene, which is the main compound in CAEO that could induce cell apoptosis in glioblastoma cell lines by inhibiting the mTOR pathway and downregulating GSTA4." (PMID 38166788, 2024).
bladder cancer (3 papers, 2007 to 2024). "Ankfn1, Gstt2, Plec, Gphn, Fmo5, Cmss1, Ahnak, Mecom, Slc2a1, Gsta4, Kras, Peak1, and Hmga2 were associated with worse disease-free survival in bladder cancer patients." (PMID 39769061, 2024). "Gstt2, Gphn, Plec Cmss1, Ahnak, Slc2a1, Gsta4, Kras, Peak1, and Hmga2 were associated with worse overall survival in bladder cancer patients, and the association was significant for Gstt2 and Ahnak." (PMID 39769061, 2024).
colon cancer (3 papers, 2022 to 2023). "In this study, we investigated the role of GSTA4 in CRC cells by deleting GSTA4 in HCT116 human colon cancer cells." (PMID 35936694, 2022). "In this study, we inactivated GSTA4 in HCT116 human colon cancer cells and investigated the effect of GSTA4 on cancer cell proliferation and chemoresistance." (PMID 35936694, 2022). "Recently, GSTA4 has also been shown to affect the progression of colon cancer, as well, and this effect involves the proapoptotic metabolite 4‐HNE." (PMID 35048517, 2022). "Accordingly, studies have shown that GSTA4 can promote the malignant progression of lung cancer, gastric cancer, colon cancer, and other tumors." (PMID 35048517, 2022). "Indeed, inactivation of GSTA4 in colon cancer cells had very limited effect on the 4-HNE detoxification." (PMID 37810110, 2023). "Specifically, in colon cancer, activator protein 1 regulates the production of 4‐HNE by affecting the c‐Jun/Nrf2 complex, which then results in an increase in the level of GSTA4 in cells." (PMID 35048517, 2022).
liver cancer (3 papers, 2022 to 2023). An epithelial or non-epithelial malignant neoplasm that arises from the liver. "GSTA4 is a member of the Phase II detoxifying enzyme superfamily and is associated with liver cancer progression." (PMID 37858159, 2023). "Previous studies have reported that decreased expression of GSTA4 is associated with positive outcomes in glioma models, whereas increased expression of GSTA4 promotes the malignant progression of liver cancer." (PMID 36699470, 2022). "In liver cancer, for example, high expression of GSTA4 promotes tumor invasion and migration in vivo and in vitro by inducing Akt phosphorylation, but little is known about the role of GSTA4 in glioma." (PMID 35048517, 2022).
melanoma (3 papers, 2020 to 2024). A malignant, usually aggressive tumor composed of atypical, neoplastic melanocytes. "Thus, the study’s findings suggest that inhibiting GSTA4 could disrupt melanoma cells’ defense mechanisms, rendering them more susceptible to immune-mediated destruction and possibly curbing their metastatic capabilities." (PMID 38791327, 2024). "Our recent findings reveal that GSTA4 is crucial in enabling melanoma cells to resist the oxidative stress induced by IFN-γ." (PMID 38791327, 2024). "In addition, the identification of glutathione-S-transferase-4 (GSTA4) upregulation in melanoma cells that have escaped the immune response marks a significant advancement in the understanding of the ability of cancer cells to evade host immunity." (PMID 38791327, 2024).
Alzheimer disease (2 papers, 2017 to 2022). A progressive, neurodegenerative disease characterized by loss of function and death of nerve cells in several areas of the brain leading to loss of cognitive function such as memory and language. "A study in Alzheimer’s disease patient tissue found GSTA4 expressed in neurons and in blood vessels." (PMID 28672859, 2017).
colitis (2 papers, 2023 to 2025). Inflammation of the colon. "Our findings show that concurrent inactivation of Gsta4 and Il10 (Il10−/−/Gsta4−/−) in mice increases susceptibility to spontaneous colitis under specific pathogen-free conditions." (PMID 39819335, 2025). "E. faecalis OG1RFSS was used to induce colitis in Gsta4−/− and Il10−/−/Gsta4−/− mice by orogastric gavage." (PMID 39819335, 2025). "In this study we utilized an AOM/DSS-induced CAC murine model to investigate the correlations of Gsta4 and 4-HNE adducts with the expression of inflammatory cytokines as well as pathological changes during colitis-associated cancer development." (PMID 37810110, 2023). "However, minimal colitis is observed in either Gsta4−/− or Il10−/−/Gsta4−/− mice following colonization with E. faecalis." (PMID 39819335, 2025). "Notably, 19.6% of Il10−/−/Gsta4−/− mice spontaneously developed colitis and, occasionally dysplasia, while housed in an SPF environment, supporting key roles for anti-inflammatory and antioxidative genes in protecting against CRC." (PMID 39819335, 2025). "In contrast, inactivation of Gsta4 inhibits MIBE by promoting macrophage death through ferroptosis and thus blocks E. faecalis-induced colitis and CRC." (PMID 39819335, 2025). "However, the roles of Gsta4 in E. faecalis-induced colitis and CRC remain unclear." (PMID 39819335, 2025). "To test this hypothesis, we colonized Gsta4−/− and Il10−/−/Gsta4−/− mice with E. faecalis OG1RFSS, or PBS as control, for 9 months and evaluated for colitis and CRC." (PMID 39819335, 2025). "We found that, unlike Il10−/− mice, Gsta4−/− and Il10−/−/Gsta4−/− mice colonized with E. faecalis failed to develop colitis or CRC." (PMID 39819335, 2025). "Notably, neither Il10−/− nor Gsta4−/− mice developed colitis when housed in an SPF environment." (PMID 39819335, 2025).
glioma (2 papers, 2022). A benign or malignant brain and spinal cord tumor that arises from glial cells (astrocytes, oligodendrocytes, ependymal cells). "Our results show that GSTA4 is highly expressed in gliomas and that its expression level is positively correlated with the degree of malignancy of gliomas." (PMID 35048517, 2022). "GSTA4 is expressed in the cerebral cortex and brainstem and is involved in the development of gliomas." (PMID 36699470, 2022). "In conclusion, inhibition of GSTA4 correlates with positive outcomes in glioma models, and thus, this molecule is a candidate drug for the treatment of glioma." (PMID 35048517, 2022). "Curzerene can induce apoptosis by inhibiting the expression of GSTA4 in gliomas, and it can downregulate the proliferation, invasion, and migration of gliomas by inhibiting the phosphorylation and activation of mTOR and the expression of MMP9." (PMID 35048517, 2022). "In this study, we investigated the effect of curzerene on GSTA4 expression in glioma, and we explored antitumor effects and mechanisms of curzerene treatment in glioma cell lines and tumor‐bearing mouse models." (PMID 35048517, 2022). "In this study, we found that curzerene can significantly inhibit the expression of GSTA4 in the glioma cell types U251 and U87." (PMID 35048517, 2022). "Curzerene was found to inhibit the expression of GSTA4 mRNA and protein in U251 and U87 glioma cells, and this effect correlated with a downregulation of the proliferation of these cells in a time‐ and dose‐dependent manner." (PMID 35048517, 2022). "This is the first report of the use of curzerene in glioma and also the first study on the relationship between the GSTA4 and malignant progression of glioma." (PMID 35048517, 2022). "Curzerene, as a traditional Chinese medicine extract, can inhibit the malignant progression of glioma by downregulating GSTA4, p‐mTOR, MMP9, and other signals." (PMID 35048517, 2022). "This positive correlation of expression with degree of malignancy of gliomas suggests that GSTA4 can promote the occurrence and development of gliomas." (PMID 35048517, 2022). "In order to determine whether curzerene affects the expression of GSTA4 in glioma, we selected the U87 and U251 glioma cell lines as experimental subjects." (PMID 35048517, 2022). "High levels of GSTA4, thus, may predict poor prognosis of disease progression in glioma patients." (PMID 35048517, 2022). "It is therefore worth exploring whether there is a similar relationship between GSTA4 and MMP9 in glioma." (PMID 35048517, 2022).